BDNF (brain derived neurotrophic factor)
Diseases named in the same sentence as BDNF in open-access papers (continued):
Sharing a sentence is not in itself a finding about the gene and the disease.
Cognitive impairment (continued). "In a longitudinal study, individuals with both BDNF Met and APOE E4 alleles exhibited more pronounced entorhinal cortex atrophy and cognitive decline over three years compared to Val/Val homozygotes in cases of mild cognitive impairment (MCI) and AD." (PMID 38916728, 2024). "Hence, in this review, we attempted to focus on the role of BDNF in autophagy, the main culprit behind cognitive impairment." (PMID 37287291, 2024). "Thus, LGG attenuates SAE-reduced BDNF expression and p-TrkB levels to maintain neuronal survival and ameliorate cognitive impairment in mice with sepsis." (PMID 38827289, 2024). "hSG and its supplement (combined with NK109) may alleviate LPS-induced systemic inflammation by suppressing NF-κB activation and inducing BDNF expression, resulting in the amelioration of cognitive impairment." (PMID 39203872, 2024). "Sodium butyrate mitigates radiation-induced cognitive impairment by mitigates inhibiting hippocampal phosphorylation of cAMP response element binding proteins or promoting the expression of brain derived neurotrophic factor (BDNF)." (PMID 37728579, 2024). "Interestingly, we found a positive correlation between sBDNF levels and the cognitive deficits in burnout nurse, showing that BDNF was positively with reasoning, memory, and attention and CAB total score." (PMID 38787900, 2024). "The decline in SIRT1/BDNF levels leading to changes in synaptic plasticity and neuronal excitability in older mice could be a significant factor contributing to cognitive impairment after anesthesia/surgery." (PMID 38783169, 2024). "It was considered that the pathological changes leading to cognitive impairment were compensated through hippocampal hyperactivation to preserve episodic memory as seen in functional MRI, which could be driven by BDNF." (PMID 39148705, 2024). "Interestingly this sphingosine-1-phosphate analog, has been shown to upregulate BDNF mRNA levels and increase BDNF protein release and to increase cognitive impairment in Huntington’s disease and Alzheimer’s diseases." (PMID 39135718, 2024). "Lastly, it is interesting to stress that elderly people with schizophrenia exhibit lower BDNF levels and more cognitive deficits than healthy controls, supporting the accelerated aging hypothesis of schizophrenia." (PMID 39517406, 2024). "This study aimed to explore the efficacy of computerized cognitive remediation therapy (CCRT) on psychiatric symptoms, cognitive deficits, and serum levels of brain-derived neurotrophic factor (BDNF) and glial cell line-derived neurotrophic factor (GDNF) in patients with schizophrenia." (PMID 39886050, 2024). "Such downregulation was also observed in Alzheimer’s disease, showing that the serum BDNF levels may be involved in the progression of cognitive impairment." (PMID 38648255, 2024). "Finally, resveratrol has been shown in vitro to have neuroprotective effects in different chemotherapy-induced cognitive impairments by acting on neuroinflammation and BDNF levels, especially hippocampal levels." (PMID 39458427, 2024). "Based on this scientific premise, we hypothesize that RT-induced impairments in neuronal function, elevated neuroinflammation, and cognitive deficits culminate following reductions in neuroprotective BDNF." (PMID 39696694, 2024). "In summary, this study suggested that intermittent sleep disturbance before surgery exacerbated microglial activation, neuroinflammation, and microglial BDNF-TrkB signalling dysfunction induced by surgery, resulting in postoperative emotional changes and cognitive impairments of aged rats." (PMID 38221533, 2024). "Therefore, BDNF plays a crucial role in Aβ-induced synaptic damage in neurons and cognitive impairment in AD patients." (PMID 39226164, 2024). "The diagnosis and treatment of cognitive deficits may consider the miRNA–BDNF mechanism, as well as BDNF and other neural plasticity mechanisms." (PMID 39062916, 2024).
Cognitive impairment (continued). "This study aimed to analyze the correlation between changes in cognitive level and skeletal muscle mass in patients undergoing hemodialysis and explore the possible mechanism by which BDNF mediates skeletal muscle mass and cognitive disorders through a mediation analysis." (PMID 38559694, 2024). "Additionally, the pre-treatment with ANA12, a TrkB antagonist, has been reported to block BDNF signaling and exacerbate cognitive impairments, further suggesting the BDNF signaling through TrkB is closely linked to cognitive dysfunction." (PMID 39683616, 2024). "The cognitive impairment of aged rats was accompanied by increased mRNA expression of neuroinflammatory factors such as IL-1beta and TNFalfa and by a decrease in the protein expression of neurotrophic factor BDNF." (PMID 37994990, 2024). "Although there are no studies assessing interactions between these SNPs and dietary contaminants in neurodevelopment, some evidence suggests that BPA may interfere with the BDNF signalling pathway, leading to behavioural and cognitive impairments." (PMID 39203776, 2024). "In addition, candesartan attenuates LPS‐induced cognitive impairment by restoring the activity of brain BDNF/TrkB in mice." (PMID 38899551, 2024). "The results above indicated that inhibiting BDNF pathway by K252a could attenuate the protective effect of rTMS intervention, and exacerbate cognitive deficits and anxiety behavior in RIBI mice." (PMID 38570868, 2024). "Moreover, our current study showed that serum BDNF significantly decreased after HFD consumption, which indicates a potential role of BDNF in the pathogenesis of obesity-induced neurobehavioral and cognitive impairment." (PMID 40255947, 2024). "Additionally, mental training has been shown to increase both BDNF and memory, while low BDNF correlated with cognitive impairment." (PMID 38398813, 2024). "BDNF mediates the relationship between cognitive impairment and skeletal muscle function." (PMID 38559694, 2024). "Other studies suggested that the serum brain-derived neurotrophic factor (BDNF) may play a role in the pathophysiology of cognitive deficits, especially delayed memory in T2D patients." (PMID 38396924, 2024). "Therefore, it is currently impossible to discern any discernible changes in serum BDNF levels in patients with mild cognitive impairment (MCI)." (PMID 39712854, 2024). "Recently, many animal (rodent) studies have revealed that IF positively stimulates the production of BDNF in the hippocampus, cerebral cortex, and striatum and reduces cognitive deficits by enhancing neurotrophic support and suppressing the expression of pro-inflammatory cytokines." (PMID 38276070, 2024). "Probiotic supplementation, specifically with Lactobacillus spp., appears to mitigate EHS-induced cognitive impairment, potentially through the modulation of the BDNF/TrKB signaling pathway within the hippocampus, illustrating the therapeutic potential of targeting the gut-brain axis." (PMID 38654189, 2024). "Therefore, to delve into the role of BDNF signaling in the mechanism by which FPF improves cognitive impairment induced by SD, a TrkB receptor antagonist was blocked." (PMID 39683616, 2024). "Interestingly, in AD, TrkB.T1 levels increase while BDNF and full-length TrkB levels in the frontal cortex and hippocampus decrease, and these elevated levels of TrkB.T1 also correlate with memory and cognitive impairments in transgenic mouse models of AD." (PMID 37508471, 2023). "As for stress-induced cognitive deficits, one earlier study reported that 14-day hippocampal BDNF infusion before chronic immobilization stress could protect adult rats from stress-induced deficits in spatial learning and memory." (PMID 37225683, 2023).
Cognitive impairment (continued). "Preclinical studies using germ-free or antibiotic-treated rodents show no or reduced microbiome diversity, respectively with significant cognitive deficits such as reduced memory, impaired working memory, and changes in brain-derived neurotrophic factor in the hippocampus." (PMID 37213047, 2023). "It was reported that the Met gene reduced active-dependent secretion of BDNF and binding of mature BDNF and TrkB and damaged the intracellular transport and synaptic location of mature BDNF, leading to synaptic plasticity dysfunction and cognitive impairment." (PMID 37876876, 2023). "Considering the role of BDNF in synaptic plasticity, which is crucial for cognitive functions, the reduced levels of BDNF in schizophrenia may contribute to the cognitive deficits observed." (PMID 37109038, 2023). "As the most downstream factor mediating EX-induced brain health, manipulating BDNF content in the brain has emerged as a promising strategy for mitigating cognitive deficits, addressing neurodegenerative disorders, counteracting age-related cognitive impairment, and promoting overall brain health." (PMID 37868812, 2023). "Interestingly, microglial activation was shown to perpetuate the decline in BDNF levels, resulting in cognitive impairment." (PMID 36943623, 2023). "For example, a study conducted in Brazil with 143 older adults reported high levels of BDNF serum concentration, above the fourth quartile (> 2,378.4 pg/mL) of BDNF concentration of the control group, in individuals with mild cognitive impairment or Alzheimer’s disease." (PMID 36629701, 2023). "The results showed that MS patients carrying the BDNF rs6265 polymorphism were 3.56 times more likely to have cognitive impairment compared with patients not carrying the polymorphism." (PMID 38136952, 2023). "The MALAT1/miR-382-3p/BDNF signaling pathway may play a key regulatory role in cognitive impairment in T2DM." (PMID 37740187, 2023). "In addition, serum BDNF levels have been found to be reduced in subjects with mild cognitive impairment (MCI) and AD and correlated with the severity of memory impairment." (PMID 37596686, 2023). "Thus, our study revealed a relationship between low peripheral BDNF levels and the thrombotic subtype of ischemic stroke with cognitive impairment in the acute period of ischemic stroke." (PMID 36969561, 2023). "Diabetes was found to be a predictor of both cognitive impairment and BDNF levels." (PMID 36936159, 2023). "EE ameliorates postsurgery SD‐induced cognitive impairments, which may be mediated by the axis of BDNF/GluA1." (PMID 37095708, 2023). "Impaired hypofunction of the dopamine system and NMDA–dependent glutamate transmission may sustain the cognitive deficits of schizophrenia by affecting intracellular trafficking and signaling of BDNF." (PMID 37240042, 2023). "Furthermore, inhibition of the compensatory increases of the BDNF-ERK-CREB pathway and exacerbates cognitive impairment in vascular dementia associated with obesity." (PMID 36830589, 2023). "AE may upregulate the expression of MALAT1 in serum-Exos to competitively inhibit miR-382-3p and upregulate BDNF expression, thus improving cognitive impairment in T2DM mice." (PMID 37740187, 2023). "The study findings imply that excessive cognitive deficits are prevalent in the early stages of schizophrenia and low BDNF levels may have a role in the aetiology of schizophrenia, although not necessarily in cognitive problems." (PMID 37077958, 2023). "In patients with these fragile characteristics, the occurrence of an acute stroke may further exacerbate higher inflammatory conditions with low BDNF levels, leading to a higher possibility of cognitive impairment." (PMID 37373767, 2023). "Moreover, BDNF is involved in 9 out of the 13 CNS-related pathological pathways examined (i.e., Huntington disease, amnestic disorder, toxic encephalopathy, cognitive disorder)." (PMID 37569576, 2023).
Cognitive impairment (continued). "Importantly, one meta-analysis found that lower levels of BDNF were found in T2DM patients only when they had cognitive impairment." (PMID 36970903, 2023). "APOE ε2/ε3/ε4 and BDNF val66met polymorphisms were found to exist in patients with poorer motor outcomes than those without their presence, coexisting with cognitive impairment in patients with BDNF val66met polymorphism." (PMID 37041905, 2023). "Given the high expression of BDNF in hippocampus neurons, it may be a useful early marker of cognitive impairment in diabetes." (PMID 36936159, 2023). "Here, for the first time, our acute experiments of local rhBDNF infusion and 7,8-DHF administration show that upregulating the BDNF-TrkB pathway restores ELS-induced spatial memory deficits, providing direct evidence that the BDNF-TrkB pathway is causally involved in ELS-induced cognitive deficits." (PMID 37225683, 2023). "Thus, MF treatment ameliorates CCH-induced cognitive impairment by regulating ERK/CREB/BDNF signaling, suggesting that MF is a therapeutic candidate for treating CCH." (PMID 37513692, 2023). "The keywords used for the selection of the pieces were focused on ‘Alzheimer’s disease’, ‘dementia’, ‘cognitive impairment’, ‘aging’, ‘oxidative stress’, ‘reactive oxygen species’, ‘biomarker’, and ‘brain-derived neurotrophic factor’ or ‘BDNF’ and those synonyms." (PMID 38053647, 2023). "This work opens the door for new targeted development of novel drugs that target cortical FKBP51, such as SAFiT2, with the potential to treat cognitive deficits, which are the most debilitating but untreated symptoms of psychiatric disorders, via BDNF-mediated synaptic plasticity." (PMID 36729133, 2023). "Importantly, ELS-induced cognitive deficits were rescued by up-regulating the BDNF-TrkB pathway function by local infusion of rhBDNF or 7,8-DHF." (PMID 37225683, 2023). "Based on the data that T2DM is a predictor of both cognition and BDNF levels, we hypothesized that BDNF may play a role in diabetes-related cognitive impairment." (PMID 36936159, 2023). "Most of the studies have found reduced BDNF levels, both in diabetic animals and human patients, in a correlation with the intensity of memory decline, suggesting the important contribution of BDNF in the pathophysiology of cognitive impairment." (PMID 38137892, 2023). "Furthermore, there is evidence that arketamine can ameliorate cognitive deficits in offspring after MIA through activation of BDNF-TrkB signaling." (PMID 36786865, 2023). "Does the BDNF-TrkB pathway mediate ELS-induced cognitive deficits?" (PMID 37225683, 2023). "Furthermore, the PAI-1/BDNF ratiowas significantly increased in Alzheimer patients as compared to amnesticmild cognitive impairment (36.4% more) and controls (40% more)." (PMID 37810633, 2023). "Moreover, higher dietary Zn intake (30 p.p.m.)was found to prevent cognitive impairments in transgenic mouse model of Alzheimer’s disease through upregulating BDNF and alleviating amyloid beta and mitochondrial dysfunction." (PMID 36977735, 2023). "This study aims to investigate the role of BDNF in cognitive impairment in prediabetes and T2DM." (PMID 36936159, 2023). "Finally, our investigation focused on determining the role of the BDNF/TrkB/CREB pathway in the long‐term cognitive impairment following HI insults and DEX treatment." (PMID 37830170, 2023). "In vivo experiments further confirmed that AE could increase the expression of MALAT1 in serum-Exos to competitively inhibit miR-382-3p and upregulate BDNF expression, thereby improving cognitive impairment in T2DM mice." (PMID 37740187, 2023). "Reduced hippocampal BDNF is highly correlated with cognitive impairment in diabetes." (PMID 37299522, 2023). "This study aimed to investigate whether DEX improves cognitive impairment by promoting hippocampal neurogenesis via the BDNF/TrkB/CREB signaling pathway in neonatal rats with HIBD." (PMID 37830170, 2023).
Cognitive impairment (continued). "In addition, nuclear factor-κB (NF-κB) activation was found to induce cognitive deficit through hindering the production of BDNF and hence, reducing synaptic plasticity." (PMID 37140732, 2023). "In addition, the PAI-1/BDNF ratiowas significantly increased in Alzheimer patients as compared to amnesticmild cognitive impairment (36.4% more) and controls (40% more)." (PMID 37810633, 2023). "Additionally, they demonstrated that the BDNF is a moderating element in a potential relationship between the severity of cognitive impairment and DPMS dysfunction." (PMID 36248031, 2022). "Therefore, regulating the level of BDNF has a certain guiding significance for the treatment of general anesthetic neurotoxicity and cognitive impairment in the developing brain." (PMID 36504660, 2022). "A clinical study reported that plasma BDNF levels were associated with cognitive impairment in non-demented middle-aged and older women." (PMID 35998179, 2022). "Decreased levels of BDNF in the hippocampus can aggravate cognitive impairment." (PMID 36389075, 2022). "LPS also decreases BDNF expression in the hippocampus, inducing cognitive impairment." (PMID 35677440, 2022). "Moreover, six months of voluntary physical exercise in 5× FAD mice rescued cognitive deficits by increasing astrocytic BDNF in the hippocampus." (PMID 35090576, 2022). "However, our study found that the way of BDNF regulating sevoflurane-induced cognitive impairment is AHN." (PMID 35309893, 2022). "Significantly, higher BDNF expression reduces cognitive impairment in the elderly." (PMID 36016853, 2022). "Other studies showed that a high ROS level could induce neuroinflammation, cellular apoptosis, and brain-derived neurotrophic factor (BDNF) dysregulation, contributing to cognitive impairment." (PMID 35767571, 2022). "Notably, lithium treatment in AD patients has been shown to increase BDNF serum values (~ 30%) and mitigate cognitive impairment." (PMID 35090576, 2022). "In addition to AD, increased production of BDNF has been shown to benefit other neurocognitive conditions such as mild cognitive impairment." (PMID 36092801, 2022). "First, future large-scale, multicenter, hospital-community prospective studies are needed to assess whether BDNF can reflect the degree of cognitive impairment and whether it can be used as a reliable predictor of cognitive impairment in children with SDB." (PMID 36683819, 2022). "As an important neuroprotective factor, the brain-derived neurotrophic factor (BDNF) may have a key role in cognitive impairment in children with sleep-disordered breathing (SDB)." (PMID 36683819, 2022). "The BDNF expression-related changes could also be responsible for the severity of anxiety and cognitive disorders." (PMID 35269761, 2022). "On the other hand, STG protected against cognitive deficits through improving oxidative stress biomarkers, inflammatory mediators, lipid profiles, and hippocampus level of BDNF as well as decreasing caspase-3 and GFAP and increasing Ki-67 immunoreactions in the hippocampus." (PMID 35265716, 2022). "The TAT-pep5 (p75 inhibitor) and the exogenous BDNF can upregulate the ratio, which may be a potential therapeutic treatment of anesthesia/surgery-induced cognitive impairment." (PMID 35370607, 2022). "As the cognitive impairment in AD is due to neurodegeneration, neurotrophic factors including brain-derived neurotrophic factor (BDNF) may slow the progression of neurodegeneration and serve as a promising strategy for AD intervention." (PMID 35090576, 2022). "Serum BDNF and TrkB levels may be promising biological indicators reflecting the severity of cognitive impairment and predicting cognitive impairment in children with SDB." (PMID 36683819, 2022). "The correlation between miR-195 and BDNF changes may play a role in GABAergic neurotransmission abnormalities and influence cognitive impairments of patients with schizophrenia." (PMID 35916975, 2022).